KIF3C (kinesin family member 3C)
Diseases named in the same sentence as KIF3C in open-access papers (continued):
Sharing a sentence is not in itself a finding about the gene and the disease.
tumor (11 papers, 2017 to 2025). "The forest plots, encompassing the 33 different tumor types, illustrated that elevated KIF3C levels were linked to an increased risk in LIHC, LUAD, MESO, SARC, STAD, and UCEC, while they were associated with a decreased risk in KIRC and LGG." (PMID 38552217, 2024). "We are committed to further exploring the specific mechanisms underlying KIF3C’s role in tumor development." (PMID 38552217, 2024). "The variations in KIF3C expression among distinct tumor types may underscore diverse underlying functions and mechanisms." (PMID 38552217, 2024). "Subsequently, we investigated the influence of KIF3C knockout on tumor cell migration through wound healing and transwell migration assays." (PMID 38552217, 2024). "The silence of KIF3C attenuated VASH2-caused chemoresistance in LUSC cells and decreased H520VASH2-xenograft tumor growth." (PMID 39443476, 2024). "We conducted an extensive analysis of KIF3C, covering its expression profile, prognostic relevance, molecular function, tumor immunity, and drug sensitivity." (PMID 38552217, 2024). "Although KIF3C is reported to promote tumor development in several cancers, the molecular mechanism remains elusive." (PMID 39443476, 2024). "As depicted in, a statistically significant positive relationship was identified between KIF3C expression levels and tumor stage (P<0.05)." (PMID 38552217, 2024). "In summary, KIF3C exhibits itself as a promising candidate for both a tumor marker and a prospective therapeutic target." (PMID 38552217, 2024). "In light of this, our study has centered on exploring the influence of KIF3C on the biological functions of tumor cells and conducting related gene analyses." (PMID 38552217, 2024). "To further evaluate the effects of KIF3C on tumorigenesis in vivo, we conducted a xenograft tumor model by subcutaneously injecting the C4-2B PCa cells." (PMID 34537760, 2021). "In the present work, our data showed that miR-150-5p was lowly expressed in NSCLC tissues, and it counteracted the oncogenic effects of KIF3C, supporting it is a tumor suppressor." (PMID 34193018, 2021). "KIF3C may inhibit tumor growth by activating the PI3K/AKT/mTOR signaling pathway, thereby prolonging the survival time of patients." (PMID 40964093, 2025). "In this study, our aim was to assess the expression of KIF3C across diverse tumor types." (PMID 38552217, 2024). "While KIF3C expression was detected in tumor and adjacent normal tissues as well." (PMID 34537760, 2021). "Until now, little information is available on KIF3C in tumor diseases and CNS disorders." (PMID 33150178, 2020). "Taken together, these findings illustrated that KIF3C knockdown blocked the VASH2-induced enhancement of EGFR endosomal recycling and rescued LUSC tumor progression and chemoresistance." (PMID 39443476, 2024). "The expression of KIF3C and ZNF513 in patient’s normal gingiva tissue was not significantly different from that in the control group, but the expression in tumor tissue was significantly increased." (PMID 37752101, 2023).
cancer (7 papers, 2017 to 2024). A tumor composed of atypical neoplastic, often pleomorphic cells that invade other tissues. "Nonetheless, the prevalence of high KIF3C expression in cancer cells and its underlying biological functional mechanisms in tumors remain uncertain." (PMID 38552217, 2024). "Notably, KIF3C expression exhibited positive associations with the pathological stages of several cancers." (PMID 38552217, 2024). "These diverse observations highlight the potential variability and complexity of KIF3C across different cancer types." (PMID 38552217, 2024). "In summary, these findings establish an inverse relationship between the level of KIF3C and the survival duration in specific cancers." (PMID 38552217, 2024). "Our data suggest that KIF3C holds the potential to function as a prognostic biomarker linked to patients’ OS, DSS, and PFS in various human cancers, particularly in instances of LGG, LUAD, MESO, STAD, and UCEC." (PMID 38552217, 2024). "Our research has revealed the significant and functional role of KIF3C as a tumorigenic gene in diverse cancer types." (PMID 38552217, 2024). "KIF3C has been reported to enhance cancer progress by regulating the phosphatidylinositol 3-kinase (PI3K)/AKT pathway and transforming growth factor beta (TGF-β) pathway." (PMID 38439082, 2024). "In comparison to normal tissues, KIF3C exhibited elevated expression across the majority of malignant tumors." (PMID 38552217, 2024). "The results of TCGA and GTEx consistently showed relatively high KIF3C expression levels in 18 types of cancer, with COAD being the exception." (PMID 38552217, 2024). "Utilizing data from publicly available databases, we conducted a comprehensive investigation into the differential expression of KIF3C across various cancer types." (PMID 38552217, 2024). "Kinesin Family Member 3C (KIF3C) assumes a crucial role in various biological processes of specific human cancers." (PMID 38552217, 2024). "It has been reported that KIF3C is considered an oncogene in several cancers." (PMID 39443476, 2024). "We also investigated KIF3C mRNA expression in CCLE cancer cell lines." (PMID 38552217, 2024). "Additionally, the GEO dataset validated the expression of KIF3C in various cancers, except for PCPG, THCA, and UCEC, and these results were consistent with those from TCGA." (PMID 38552217, 2024). "KIF3C is an oncogene that contributes to drug resistance in cancer." (PMID 38439082, 2024). "Notably, there is accumulating evidence highlighting the regulatory role of KIF3C in cancer." (PMID 38552217, 2024). "Importantly, accumulating evidence supports the regulatory function of KIF3C in cancer biology." (PMID 34193018, 2021). "Our study initially procured pan-cancer data via the UCSC Xena platform to investigate the expression levels and prognostic significance of KIF3C." (PMID 38552217, 2024). "Thus it was hypothesized that KIF3C could probably play a cancer-promoting role in NSCLC." (PMID 34193018, 2021). "We further unveiled that heightened KIF3C expression served as a prognostic indicator, and its elevated levels correlated with unfavorable clinical outcomes, encompassing reduced OS, DSS, and PFS in several cancer types." (PMID 38552217, 2024). "Moreover, by utilizing TISCH TCGA datasets, we assessed the KIF3C levels in single cells paired tumors and normal samples, uncovering elevated expression in endothelial cells in STAD in only 10 types of cancer tissues." (PMID 38552217, 2024).
KIF3C also shares sentences with these, for which no sentence is quoted: non-small cell lung carcinoma (2 papers); esophageal cancer (1); gingival hyperplasia (1); glioblastoma (1); infection (1); kidney disease (1); lung squamous cell carcinoma (1); melanoma (1); metastatic disease (1); small cell lung carcinoma (1); steatosis (1).